LY6D (lymphocyte antigen 6 family member D)
Description:
May act as a specification marker at earliest stage specification of lymphocytes between B- and T-cell development. Marks the earliest stage of B-cell specification.
Synonyms: Ly-6D; E48
Tractability: Antibody: its Gene Ontology location is reachable by antibodies, with high confidence; UniProt places it where antibodies can reach, with medium confidence; UniProt predicts a signal peptide or a membrane-spanning region.
Gene: Protein-coding gene on chromosome 8 (142,784,882 to 142,786,539, reverse strand). Ensembl gene ENSG00000167656.
Subcellular location: Cell membrane
Pathways (Reactome):
Metabolism of proteins: Post-translational modification: synthesis of GPI-anchored proteins
Gene Ontology:
Molecular function: protein binding
Biological process: cell adhesion; lymphocyte differentiation
Cellular component: cell surface; extracellular region; membrane; plasma membrane
Genetic constraint (gnomAD): Loss-of-function variants: 7 observed, 4.88 expected, observed/expected ratio (o/e) 1.44, 90% interval 0.77 to 1.92. That is too few expected variants to judge how well the gene tolerates losing a copy. Missense variants: 148 observed, 163.82 expected, observed/expected ratio (o/e) 0.9, 90% interval 0.79 to 1.03. Synonymous variants: 81 observed, 75.39 expected, observed/expected ratio (o/e) 1.07, 90% interval 0.9 to 1.29.
Homologues: Orthologues: chimpanzee LY6D (98% identical), macaque LY6D (80% identical), pig LY6D (63% identical), dog LY6D (62% identical), mouse Ly6d (59% identical), rat Ly6d (56% identical), guinea pig LY6D (53% identical), Caenorhabditis elegans D1081.20 (28% identical). Paralogues in human: LYNX1 (31% identical).
Diseases named in the same sentence as LY6D in open-access papers:
LY6D is named in the same sentence as 57 diseases in open-access papers, as found by Europe PMC text mining. Sharing a sentence is not in itself a finding about the gene and the disease. The quoted sentences say what the papers report.
pancreatic cancer (8 papers, 2011 to 2025). "Through co-culture experiments with fibroblasts, we uncovered the underlying mechanism of LY6D in regulating taurine metabolism imbalance within the immunosuppressive microenvironment of pancreatic cancer." (PMID 40230840, 2025). "In addition, through the analysis of immune infiltration of LY6D in different cohorts of pancreatic cancer, it can be observed that LY6D is mainly associated with fibroblast infiltration and has little relationship with other immune cells." (PMID 40230840, 2025). "The results showed that cells with high LY6D expression were concentrated in the tumor core of pancreatic cancer, and there was a statistically significant difference." (PMID 40230840, 2025). "Combining the literature review and the current research basis, LY6D was selected as a candidate marker linking taurine metabolism and immune resistance in pancreatic cancer." (PMID 40230840, 2025). "The results showed that LY6D was highly expressed in pancreatic cancer cells such as PANC-1, MIA-Paca2, and BxPC-3, and was most highly expressed in MIA-Paca2." (PMID 40230840, 2025). "Combined with the literature review and the current research foundation, LY6D was selected as a candidate marker linking taurine metabolism and immune resistance in pancreatic cancer." (PMID 40230840, 2025). "Further in-depth research on the mechanism of LY6D in the relationship between taurine metabolism and immunotherapy is anticipated to proffer novel targets and strategies for the treatment of pancreatic cancer." (PMID 40230840, 2025). "We observed that the LY6D protein expression was markedly higher in pancreatic cancer tissues than in normal pancreatic tissues." (PMID 37601684, 2023). "The mRNA expression data across multiple studies shows that ovarian, colorectal, gastric, breast, lung, brain and CNS, cervical, esophageal, head and neck and pancreatic cancers express significant high levels of Ly6D, Ly6E, Ly6H, Ly6K." (PMID 26862846, 2016). "Ly6D mRNA expression was increased significantly in pancreatic cancer (n=75) than normal tissues (n=55) in Pei and Badea studies." (PMID 26862846, 2016). "High Ly6D mRNA expression in pancreatic cancer was significantly correlated with decreased three-year survival (dead, n=19 vs alive, n=5) in Collisson study." (PMID 26862846, 2016). "This indicated that LY6D was specifically located in the tumor core region of pancreatic cancer tissue, strengthening our previous speculation that it could be a tumor marker." (PMID 40230840, 2025). "We hypothesized that LY6D might be an important factor promoting the transformation of the “hard cancer” characteristics of pancreatic cancer, which made it impossible for T cells to attack the tumor core region, resulting in immunosuppression." (PMID 40230840, 2025). "We experimentally verified the expression level of LY6D in common pancreatic cancer cells." (PMID 40230840, 2025). "Finally, we confirmed that the LY6D protein and mRNA expression were markedly higher in pancreatic cancer than in normal pancreatic tissue." (PMID 37601684, 2023). "LY6D, LY6E, PSCA, and PLAUR, known markers tumorigenesis and cancer cell maintenance, were significantly associated with lower overall survival outcome in our pancreatic cancer analysis." (PMID 33613843, 2021). "Unraveling the role of LY6D in these processes may lead to the development of innovative therapeutic approaches that specifically target this molecule to improve the treatment of pancreatic cancer." (PMID 40230840, 2025). "Together, our analysis and previous research suggests that LY6D expression may indicate a more aggressive pancreatic cancer phenotype and it would therefore be beneficial to explore the precise mechanism of action for LY6D to determine its therapeutic potential." (PMID 33613843, 2021). "Highlighting its utility, we show LY6D expression in other cancers, such as the ASCP subtype of pancreatic cancer, which correlates with extremely poor clinical outcomes." (PMID 36473848, 2022).
pancreatic cancer (continued). "The expressions of LY6D, BCAT1, and ITGB6 in 120 cases of pancreatic cancer and 30 cases of para-carcinoma were detected by immunohistochemistry." (PMID 34976806, 2021). "A 3-gene signature consisting of LY6D, BCAT1, and ITGB6 based on 538 DEGs between both subtypes serves as a stable prognostic marker in patients with pancreatic cancer across multiple cohorts." (PMID 34976806, 2021). "Our immunohistochemical results showed that LY6D, BCAT1, and ITGB6 were all overexpressed in pancreatic cancer, which was consistent with the previous results." (PMID 34976806, 2021). "Previous studies demonstrated that LY6D is highly expressed in colorectal cancer and that also LY6E is in pancreatic cancer stem cells." (PMID 21063397, 2011). "The LY6D, BCAT1, and ITGB6 genes were upregulated in pancreatic cancer samples." (PMID 34976806, 2021). "LY6D, LY6E, LY6H, and LY6K have increased mRNA expression in tumor tissues of ovarian, colorectal, gastric, breast, lung, bladder, brain, cervical, esophageal, head and neck, and pancreatic cancer compared to adjacent normal tissues." (PMID 33613843, 2021). "Finally, the molecular mechanisms by which LY6D, BCAT1, and ITGB6 drive the malignant progression of pancreatic cancer require further verification." (PMID 34976806, 2021).
bladder cancer (7 papers, 2016 to 2025). "One study that analyzed gene expression data of Ly6 family members found that several proteins, including LY6D, are overexpressed across various cancers, and notably, high LY6D expression is associated with poorer survival in patients with bladder cancer, ovarian cancer, and breast cancer." (PMID 40740240, 2025). "LY6D is a marker of urothelial and squamous differentiation that may add useful diagnostic and prognostic information to better guide the clinical management of bladder cancer, given that the presence of variant histology is taken into account." (PMID 33042546, 2020). "A total of 199 plasma proteins were found to be significantly associated with bladder cancer risk, among which five proteins (SLURP1, LY6D, WFDC1, NOV, and GSTM3) emerged as core candidate targets." (PMID 40740240, 2025). "LY6D is thought to play a role in multiple tumor types, including bladder cancer, breast cancer, and other epithelial-origin cancers." (PMID 40740240, 2025). "In summary, through a proteome-wide large-scale two-sample MR analysis combined with colocalization analysis, we identified SLURP1, LY6D, WFDC1, NOV, and GSTM3 as potential plasma proteins associated with bladder cancer." (PMID 40740240, 2025). "Taken together, SLURP1 and LY6D likely contribute to bladder cancer through indirect effects on the tumor microenvironment and immune regulation." (PMID 40740240, 2025). "Meanwhile, the colocalization probability (PP.H3+PP.H4 > 0.7) in our analysis indicates that the LY6D expression trait and bladder cancer risk share a common genetic locus, further strengthening the evidence for LY6D's involvement in bladder cancer." (PMID 40740240, 2025). "Subsequent colocalization analysis highlighted SLURP1, LY6D, WFDC1, NOV, and GSTM3 as being closely linked to bladder cancer occurrence." (PMID 40740240, 2025). "Lymphocyte antigen six superfamily member D (LY6D) has been identified as a biomarker for bladder cancer and a chemoresistance marker laryngeal squamous cell carcinoma." (PMID 36386788, 2022). "LY6K and LY6D are consistently upregulated across many cancers and show increased expression in bladder cancer." (PMID 33213418, 2020). "As a result, expression levels of CASK (p = 0.024), LAMA2 (p = 0.040), LY6D (p = 0.018), and CLDN4 (p = 0.043) were significantly associated with the overall survival of patients with urinary bladder carcinoma." (PMID 30699951, 2019). "Ly6D mRNA expression was significantly higher in superficial bladder cancer (n=179) than infiltrating bladder cancer (n=175) in Sanchez-Carbayo, Stransky and Lee studies." (PMID 26862846, 2016). "The gene expression analysis showed that bladder cancer expresses significant high levels of Ly6D, Ly6E, Ly6K." (PMID 26862846, 2016). "The colocalization analysis revealed that, among the 115 plasma proteins associated in the Olink dataset, three proteins - SLURP1, LY6D, and WFDC1 - exhibited strong evidence of colocalization with bladder cancer risk loci (PP.H3+PP.H4 values ~0.9999, 0.9998, and 0.758, respectively)." (PMID 40740240, 2025). "Meanwhile, LY6D might influence bladder cancer progression through interactions with non-coding RNAs or other proteins, complex mechanisms that may not be captured by traditional SMR analysis." (PMID 40740240, 2025). "SLURP1 and LY6D both belong to the lymphocyte antigen 6 (Ly6) superfamily, which typically play roles in immune responses, and they may influence the tumor microenvironment by modulating immune evasion mechanisms of bladder cancer cells." (PMID 40740240, 2025). "On the other hand, our findings indicate that the genes SLURP1, LY6D, and WFDC1 may influence bladder cancer development through more indirect or context-specific pathways, rather than through direct causal mechanisms detectable by MR alone." (PMID 40740240, 2025).
breast carcinoma (7 papers, 2016 to 2025). "In several malignancies, such as laryngeal squamous cell carcinoma, breast cancer, and lung cancer, LY6D is associated with tumor progression, metastasis, and poor prognosis." (PMID 41595468, 2025). "Ly6D mRNA expression was increased significantly in breast cancer (n=1597) than normal tissues (n=153) in Curtis study and Lin study." (PMID 26862846, 2016). "LY6D immunoreactivity was related to the invasiveness of ER positive breast cancer patients." (PMID 35395711, 2022). "LY6D may serve as a prognostic maker for advanced prostate cancer and oestrogen receptor-positive breast carcinomas." (PMID 32415241, 2020).
prostate carcinoma (6 papers, 2016 to 2023). A carcinoma that arises from epithelial cells of the prostate gland. "It has already been reported that LY6D can be used as a prognostic biomarker of advanced prostate cancer associated with prostate CSCs." (PMID 38067506, 2023). "It has been found that LY6D can be a prognostic factor for advanced prostate cancer, which is positively correlated with poor outcomes of patient survival." (PMID 38067506, 2023). "A member of the LY6 family, LY6D, contributes to the progression of basosquamous and prostate cancer." (PMID 38067506, 2023). "LY6D serves as a marker of luminal progenitors with bi-lineage capacity and intrinsic castration-resistant properties in prostate cancer." (PMID 33613843, 2021). "This analysis showed that four different members Ly6D, Ly6E, Ly6H or Ly6K have increased gene expressed in bladder, brain and CNS, breast, colorectal, cervical, ovarian, lung, head and neck, pancreatic and prostate cancer than their normal counter part tissues." (PMID 26862846, 2016). "LY6D has previously been suggested to be a suitable biomarker for differentiation between urothelial and prostate cancer, the latter being completely negative for LY6D expression." (PMID 33042546, 2020).
laryngeal squamous cell carcinoma (5 papers, 2021 to 2025). A squamous cell carcinoma that arises from the larynx. "High expression of LY6D was linked to the emergence of neck metastases and chemoresistance in laryngeal squamous cell carcinoma." (PMID 37064125, 2023). "LY6D was a drug-resistant marker gene and therapeutic target for laryngeal squamous cell carcinoma." (PMID 34169093, 2021).
lung carcinoma (5 papers, 2016 to 2025). "The LY6 family, consisting of Ly6D, Ly6E, Ly6K and Ly6H, is also associated with poor survival in several cancer types, including lung cancer." (PMID 35574342, 2022). "We found that Ly6d+ tumor cells also expressed Ki67, which is a marker of cell proliferation and whose expression is associated with a poor outcome in lung cancer." (PMID 33348616, 2020). "Recently, aberrant DNA hypermethylation in the LY6D gene promoter region has been reported in several tumours such as a gefitinib-resistant lung cancer cell line and helicobacter-associated gastric cancer in mice." (PMID 32415241, 2020). "Survival data for breast and lung cancer show that Ly6D, Ly6E and Ly6K were poor prognosis marker for these cancers." (PMID 26862846, 2016). "Ly6D mRNA expression was increased significantly in lung cancer (n=453) than normal tissues (n=244) in Landi, Selamat, Su, Okayana, Bhattacharjee, Hou, Wachi studies." (PMID 26862846, 2016). "Our results thus suggest that LY6D is a potential lung cancer stem cell marker." (PMID 33348616, 2020).
colorectal cancer (4 papers, 2011 to 2021). A primary or metastatic malignant neoplasm that affects the colon or rectum. "Ly6D mRNA expression was increased significantly in colorectal cancer (n=369) than normal tissues (n=150) in The Cancer Genome Atlas (TCGA), Sabates-Bellver, Kaiser, Gaedcke and Skrzypczak studies." (PMID 26862846, 2016). "Ly6D mRNA expression was significantly upregulated in microsatellite instability in gastric and colorectal cancer as seen by D'Errico and Jorissen studies." (PMID 26862846, 2016).
head and neck cancer (4 papers, 2009 to 2022). A primary or metastatic malignant neoplasm affecting the head and neck. "As a membrane-bounded protein with a glycosylphosphatidylinositol anchor, lymphocyte antigen 6 complex locus D (LY6D) has an established role in the adhesion of head and neck cancer cells to endothelial cells in HNSCC patients." (PMID 36430813, 2022). "LY6D plays an important role in the adhesion of head and neck cancer cells to endothelial cells, and is detected of micrometastases in lymph nodes of patients with HNSCC." (PMID 32415241, 2020). "Ly6D mRNA expression was increased significantly in head and neck cancer (n=56) than normal tissues (n=41) in Estilo, He and Frierson studies." (PMID 26862846, 2016). "Promising markers for head and neck cancers include parathyroid hormone-like hormone (PTHLH, also known as PTHrP), serpin peptidase inhibitor, clade B (ovalbumin), member 3 (SERPINB, also known as SCCA), and lymphocyte antigen 6 complex, locus D (LY6D, also known as E48)." (PMID 19961621, 2009).
head and neck squamous cell carcinoma (4 papers, 2007 to 2023). A squamous cell carcinoma that arises from any of the following anatomic sites: lip and oral cavity, nasal cavity, paranasal sinuses, pharynx, larynx, and salivary glands. "In head and neck squamous cell carcinoma, LY6D is highly expressed, and it may speed up tumor growth by causing the release of angiogenic factors." (PMID 37064125, 2023). "One cluster included Keratin 14, 17 and LY6D; Keratin 17 is a known human basal-like tumor marker, while LY6D is a member of the Ly6 family of glycosylphosphatidylinositol (GPI)-anchored proteins that is highly expressed in head and neck squamous cell carcinomas." (PMID 17493263, 2007).
squamous cell carcinoma (4 papers, 2020 to 2024). A carcinoma arising from squamous epithelial cells. "LY6D+ tumor cells are spatially localized and possess basal cell carcinoma and squamous cell carcinoma-like features." (PMID 36473848, 2022). "Apart from its involvement in cell adhesion, LY6D also regulates important interactions between endothelial cells and head and neck squamous cell carcinoma cells." (PMID 34976806, 2021). "Given the overall reduced expression of LY6D in MIBC, and in lymph node metastases, it is not likely to be a highly specific biomarker for identification of metastases from urothelial tumours, but might be helpful if the staining is positive and if squamous cell carcinoma can be excluded." (PMID 33042546, 2020).
colon cancer (3 papers, 2016 to 2024). "Our earlier studies on the LY6/uPAR superfamily member LY6D has shown that the silencing of LY6D expression suppressed colon cancer in xenograft mice." (PMID 39727968, 2024). "In brief, the results demonstrated that LY6D knockdown can suppress colon tumor growth and improve the survival rate of experimental mice." (PMID 38067506, 2023). "This study explored the role of lymphocyte antigen 6 family member D (LY6D) in colon cancer stem cells’ (CCSCs) proliferation and invasion." (PMID 38067506, 2023). "In conclusion, these findings indicate that LY6D, which is highly expressed in CCSCs, is a key factor involved in tumor growth and development and might be a potential cancer marker and therapeutic target for colon cancer." (PMID 38067506, 2023). "Moreover, the results indicated that LY6D regulates CCSC proliferation and invasion in colon cancer through the MAPK pathway." (PMID 39727968, 2024).
ovarian carcinoma (3 papers, 2016 to 2025). A malignant neoplasm originating from the surface ovarian epithelium. "High Ly6D mRNA expression in ovarian cancer was significantly correlated with poor outcome in five-year post progression free survival (low Ly6D, n=517; high Ly6D, n=190; HR=1.22, p=0.049) shown by KM plotter." (PMID 26862846, 2016). "Ly6D mRNA expression was increased significantly in ovarian cancer (n=221) than normal tissues (n=18) in Wachi, Welsh, Hendrix and Bonome studies." (PMID 26862846, 2016). "In addition, high Ly6D expression is significantly correlated with poor clinical outcome in ovarian cancer." (PMID 33299855, 2020).
gastric cancer (2 papers, 2016 to 2020). A primary or metastatic malignant neoplasm involving the stomach. "Ly6D mRNA expression was increased significantly in gastric cancer (n=31) than normal tissues (n=19) in Cho study." (PMID 26862846, 2016). "The survival data for colorectal, ovarian and gastric cancer showed that all four studied genes Ly6D, Ly6E, Ly6H, Ly6K are poor prognosis markers for multiple cancer types." (PMID 26862846, 2016). "High Ly6D mRNA expression in gastric cancer was significantly correlated with poor outcome in five-year post progression free survival (low Ly6D, n=209; high Ly6D, n=432; HR=1.38, p=0.0047) shown by KM plotter." (PMID 26862846, 2016).